LINC01193 (long independently transcribed non-coding RNA 1193)
Synonyms: LOC348120; CT60
Gene: Long non-coding RNA gene on chromosome 15 (20,940,380 to 21,058,440, forward strand). Ensembl gene ENSG00000258710.
Diseases named in the same sentence as LINC01193 in open-access papers:
LINC01193 is named in the same sentence as 11 diseases in open-access papers, as found by Europe PMC text mining. Sharing a sentence is not in itself a finding about the gene and the disease.
LINC01193 shares sentences with these, for which no sentence is quoted: autoimmune disease (4 papers); cancer (2); autoimmune disorders (1); autoimmune hypothyroidism (1); autoimmune thyroid disease (1); Graves disease (1); Insulin resistance (1); pemphigus foliaceus (1); rheumatoid arthritis (1); tumor (1); type I diabetes (1).